RNU7-74P (RNA, U7 small nuclear 74 pseudogene)
Synonyms: U7.74
Gene: Small nuclear RNA gene on chromosome 4 (40,377,452 to 40,377,513, reverse strand). Ensembl gene ENSG00000239010.
Homologues: Orthologues: macaque U7 (89% identical). Paralogues in human: RNU7-28P (89% identical), RNU7-7P (89% identical), RNU7-143P (84% identical), RNU7-14P (84% identical), RNU7-34P (84% identical), RNU7-35P (84% identical), RNU7-3P (84% identical), RNU7-6P (84% identical), RNU7-11P (82% identical), RNU7-124P (82% identical), RNU7-190P (82% identical), RNU7-20P (82% identical), and 141 more.